STAT3 (signal transducer and activator of transcription 3)
Diseases named in the same sentence as STAT3 in open-access papers (continued):
Sharing a sentence is not in itself a finding about the gene and the disease.
breast cancer (continued). "For example, in T-47D and SK-BR-3 breast cancer cell lines, STAT5a and STAT3 differentially regulated BCL-6 expression, a protein involved in apoptosis." (PMID 32633727, 2020). "JAK2/STAT3 signaling has been reported to be responsible for the maintenance of CD44+/CD24− stem like-cell populations isolated from human breast cancer cells." (PMID 32503225, 2020). "IHT has not been studied extensively in human cancers, but a recent study reported that it inhibited the phosphorylation of Stat3 and proliferation of breast cancer cells." (PMID 33172112, 2020). "According to previous studies, interleukin-6 (IL-6) can activate JAK2/STAT3 signaling, and repression of the IL-6/JAK2/STAT3 signaling axis has been reported to inhibit the migration, invasion, and tumor formation of breast cancer cells." (PMID 32503225, 2020). "IL-6 is a strong stimulator of STAT3 pathway which is important in regulating survival and growth of breast cancer cells." (PMID 32649314, 2020). "STAT3 silencing in breast cancer cells or the ablation of T cell STAT3 led to a reduced STAT3-mediated PD-L1 expression, and reduced breast tumour development." (PMID 32731620, 2020). "Recent study from our group reported that STK11 plays an important role in mediating anti-cancer effects of HNK leading to inhibition of cancer stem-like phenotype in breast cancer by direct inhibition of oncogenic Stat3 signaling." (PMID 32963809, 2020). "Circulating levels of FABP4 are markedly increased in obese individuals due to release from an expanded adipose tissue depot and FABP4 can induce mammary tumor stem cells by enhancing ALDH1 activity via IL-6/STAT3 signaling." (PMID 33339340, 2020). "We demonstrated that PP and PL in combination inhibit STAT3 phosphorylation and regulate downstream molecules to induce apoptosis in breast cancer cells." (PMID 31948057, 2020). "MiR-93 suppresses WNK1 to reduce breast cancer malignancy, while it enhances the expression of STAT3." (PMID 32612456, 2020). "In the context of breast cancer, STAT3 signaling has been shown to be required for maintenance of self-renewal and growth of CD44+ breast CSCs." (PMID 33335857, 2020). "In our study, PSD-A restricted cell growth, inhibited STAT3 activation and induced apoptosis and autophagy in breast cancer cells via ROS generation and Ca+2 oscillation." (PMID 33013353, 2020). "NPY5R is known to induce proliferation via MEK in cardiomyocytes, bone marrow stromal cells and breast cancer cells, and STAT3 in vascular smooth muscle cells." (PMID 31915051, 2020). "exportin-1 inhibition with the selinexor analogue KPT-276 has been shown to repress STAT3 activation and survivin transcription in breast cancer cell lines." (PMID 32231398, 2020). "For example, STAT3 in TAMs from breast cancer is overactivated, which inhibits the expression of IL-12 and significantly promotes the secretion of TNF-α." (PMID 33005103, 2020). "For example, a platinum (IV) compound called IS3 295 blocked STAT3-DNA binding properties to induce apoptosis in breast cancer." (PMID 33266219, 2020). "Compelling experimental evidence from both clinical trials and animal studies demonstrated that the JAK2/STAT3 pathway plays a pivotal role in the initiation, progression, and metastasis of breast cancer." (PMID 32922496, 2020). "According to several pre-clinical investigations, activated STAT3 can play a regulatory role in breast cancer therapy resistance and tumorigenesis." (PMID 32503225, 2020). "STAT3/survivin signaling regulates a poor response to radiotherapy in HER2-positive breast cancer, ESCC and lung cancer." (PMID 32872659, 2020). "This systematic review discusses the advances in the discovery of the STAT3 pathways and drugs targeting STAT3 in breast cancer." (PMID 32111215, 2020).
breast cancer (continued). "Faecalibacterium prausnitzii suppresses the growth of breast cancer cells through inhibition of IL-6/STAT3 pathway." (PMID 32272885, 2020). "Previous work has demonstrated that LIF can induce STAT3 signaling in breast cancer cells, and STAT3 has been previously identified as a pro-dormancy factor in ER+ breast cancer cells and prevents colonization of the bone by disseminated tumor cells." (PMID 32023849, 2020). "miR-874 contributes to inhibit tumor angiogenesis through targeting STAT3 in gastric cancer, which can also inhibit cell proliferation and induce apoptosis in human breast cancer by targeting cyclin-dependent kinase 9 (CDK9)." (PMID 32908641, 2020). "STAT3 also established an immunosuppressive microenvironment to promote the growth and metastasis breast cancer." (PMID 32733808, 2020). "A recent study revealed that TM4SF1 coupled with DDR1 was shown to promote cancer stem cell traits and metastatic reactivation and by PKCα-dependent JAK2/Stat3 signalling in breast cancer." (PMID 33153498, 2020). "The STAT3-IKKα interaction plays a crucial role for IKKα stabilization, which can provide a novel therapeutic target for breast cancer treatment." (PMID 33396715, 2020). "Recently, we reported that tubulosine inhibited JAK2/STAT3 signalling in IL‐6‐induced breast cancer." (PMID 32558259, 2020). "Signal transducer and activator of transcription 3 (STAT3) is an early tumor diagnostic marker and is known to promote breast cancer malignancy." (PMID 32111215, 2020). "Sun and colleagues found that pharmacological inhibition of STAT3 with S32-201 reduced breast cancer cell EMT and stem-like properties." (PMID 32391382, 2020). "Ruxolitinib inhibited STAT3 activation and decreased cell growth in breast cancer, NSCLC, HNC, esophageal cancer, bladder cancer, HCC, cervical cancer, and colorectal cancer cell lines." (PMID 33521321, 2020). "As a consequence, the nuclear translocation of STAT3 is inhibited, and its attachment into paxillin is suppressed, leading to the downregulation of angiogenesis and invasion and migration of breast cancer cells." (PMID 32380783, 2020). "In contrast to ER+ breast cancer, both HER2+ and TNBC have elevated levels of IL-6, causing an autocrine feedback loop through IL-6-activated STAT3." (PMID 32023849, 2020). "STAT3 was also shown to locate to the mitochondria and regulate its function, increasing growth and metastasis in breast cancer by protecting it from the cytotoxic effect of reactive oxygen species (ROS)." (PMID 33266219, 2020). "As the bulk supporting tissue of breast cancer, IL-6 and leptin release by white adipose tissue has been correlated with paracrine activation of STAT3 (canonical) thereby driving metastatic process." (PMID 32331320, 2020). "Collectively, these results indicate that STAT3 inhibits the capacity of an in vitro-generated CD103+ cDC1 vaccine to induce systemic anti-tumor immunity in murine breast cancer." (PMID 31947933, 2020). "In other words, STAT3 expression was correlated with sensitivity to abiraterone in breast cancer cell lines." (PMID 32486001, 2020). "Recently, it has been shown that an obesity-associated increase in FAO in CD8+ T effector cells was orchestrated by the Programmed death-1 (PD-1) activation of STAT3 signalling, and this pathway had a key role in breast cancer progression." (PMID 32731620, 2020). "Experimental evidence implicated S1PR1 coupled to Gi and persistently triggered STAT3, mitogen-activated protein kinase (MAPK) and AKT signaling pathways, to promote many types of tumor growth and metastasis including breast cancer." (PMID 33101013, 2020). "By suppressing JAK2 kinase activity, parthenolide also suppressed STAT3 phosphorylation induced by IL-6 in breast cancer (MDA-MB-231) cells." (PMID 32545187, 2020). "In breast cancer, a novel small molecule Rac1/Cdc42 dual inhibitor, MBQ-167, impaired STAT3 activation, resulting in decreased metastatic breast cancer cell migration." (PMID 32915198, 2020).
breast cancer (continued). "The suppression of STAT3 signaling has been reported to promote apoptosis in several human cancer cells including breast cancer cells." (PMID 32503225, 2020). "Our results also suggest IL-10 is a key factor eliciting immunosuppressive STAT3 signaling in CD103+ cDC1s in breast cancer." (PMID 31947933, 2020). "In breast cancer, up-regulated miR-495 can inhibit cell proliferation and promote apoptosis by targeting STAT-3." (PMID 32450789, 2020). "Many studies have also demonstrated that Stat3 phosphorylation and activation upregulate the expression of cMyc and Sox2, which promote the self-renewal of breast cancer cells." (PMID 32630026, 2020). "This study proposes the use of pentadecanoic acid as a novel JAK2/STAT3 inhibitor in breast cancer therapy." (PMID 32503225, 2020). "The aim is to investigate the mechanism of HIF‐1α and signal transducer and activator of transcription‐3 (STAT3) interaction and discover a compound to disrupt the interaction in breast cancer cells." (PMID 32065498, 2020). "The implication of cancer cells in ATR knockdown in CAFs has been proven in vitro by showing that breast cancer cells downregulate ATR in breast fibroblasts in an IL-6/STAT3-dependent manner and via AUF-1." (PMID 32414408, 2020). "The co-expression and coordinated oncogenic functions of IKKα and STAT3 imply a cross-talk between these two signaling proteins in human breast carcinoma." (PMID 33396715, 2020). "In the subsequent study, we observed the co-expression of STAT3 and IKKα in human breast carcinoma tissues." (PMID 33396715, 2020). "Breast cancer-derived EV have been demonstrated to induce an IL-6-mediated pathway via gp130/STAT3 signaling, leading to TAM polarization." (PMID 32878277, 2020). "Mechanistically, we demonstrated that carnosol suppressed the activation of STAT3 signaling pathway through a ROS-dependent targeting of STAT3 to proteasome-degradation in breast cancer cells (MDA-MB-231, Hs578T, MCF-7, and T47D)." (PMID 31456939, 2019). "Added to that, these authors also showed that MMP-9 expression correlates with that of activated Stat3 in human breast cancer specimens." (PMID 31456939, 2019). "Our prior studies showed that a high level of visfatin in human breast cancer tissues correlated with tumor progression mediated by cAbl and STAT3, using breast cancer cell lines." (PMID 31861872, 2019). "The results showed that STAT3 or p-STAT3 expression in breast cancer tissues was much higher than that in normal ones, indicating a positive correlation between STAT3 or p-STAT3 overexpression and the occurrence of breast cancer." (PMID 31375715, 2019). "In conclusion, we discovered ODZ10117 as a novel STAT3-specific inhibitor for STAT3-targeted cancer therapy and demonstrated its anticancer activity in breast cancer models." (PMID 31684051, 2019). "Accumulating research has shown that how STAT3 constitutively activated in numerous types of cancer, including multiple myeloma, lymphomas, head and neck squamous cell carcinoma, breast cancer, prostate cancer, and hepatocellular carcinoma (HCC)." (PMID 30847297, 2019). "The treatment of human breast cancer cells with MH led to a dose and time-dependent inhibition of the transcriptional activity of STAT3." (PMID 31491838, 2019). "In particular, STAT3, a transcription factor stimulated by IL-6, was shown to be consistently expressed in most breast cancer cells." (PMID 31252615, 2019). "We first measured STAT3 expression levels in several molecular subtypes of breast cancer cell lines and observed that STAT3 was phosphorylated persistently in TNBC cell lines." (PMID 31058868, 2019). "The results showed that the STAT3/p-STAT3 expression level in breast cancer of the late stage was much higher than the early stage (OR = 3.58, 95% CI = 2.44–5.25)." (PMID 31375715, 2019). "Signal transducer and activator of transcription 3 (STAT3) is selectively activated by IL-6 and thought to be constitutively expressed in more than 50% of breast cancers." (PMID 31252615, 2019).
breast cancer (continued). "Meta-analysis was used to assess and evaluate the literature reporting the correlations between STAT3/p-STAT3 and breast cancer, with an attempt to decrease the bias of literature and to provide new therapeutic strategy to Chinese women’s breast cancer." (PMID 31375715, 2019). "Other investigations of STAT3 have confirmed the involvement of this protein in breast cancer malignancies." (PMID 31064156, 2019). "Generally, the experimental results evidenced that CAPE-pNO2 likely via inhibiting the EGFR/STAT3/Akt/E-cadherin signaling pathway to against growth and metastasis of breast cancer in vivo and in vitro." (PMID 31214503, 2019). "Human breast cancers infrequently (~7%) show signs of STAT5 activation (compared to 40% of STAT3 activation)." (PMID 31684144, 2019). "It has been previously reported that targeting upstream signals via dual inhibition of STAT1 and STAT3 completely downregulates PD-L1 expression in breast cancer cells." (PMID 31505846, 2019). "In breast cancer cells, STAT3 activation is involved in a large number of phenotypic responses such as cell proliferation, survival, anti-apoptosis, angiogenesis and metastasis." (PMID 31040267, 2019). "Recently, STAT3/IL6 was reported to mediate signalings endowing breast cancer cells with stem-like properties." (PMID 31709178, 2019). "In each way, we regard STAT3 gains more significance as a therapeutic target in breast cancer bone metastases." (PMID 31040267, 2019). "In human breast cancer, STAT3 is critical in survival and proliferation of tumor-correlated cells, which are tumor-supporting cells and, also, is a promoter in the human breast progression and breast tumor progression." (PMID 31485222, 2019). "STATTIC inhibits STAT3 DNA binding activity and slows the growth of xenograft tumors representing breast cancer and head and neck squamous cell carcinoma." (PMID 31671769, 2019). "Previous studies showed that ANXA2 modulates STAT3 phosphorylation (p-STAT3) levels to stimulate proliferation, angiogenesis, metastasis and epithelial to mesenchymal transition in breast cancer cells." (PMID 30898167, 2019). "Recently, a study reported that Notch4/STAT3 crosstalk is important for EMT in breast cancer, and IHC assays showed that Jagged1 and STAT3 protein were both expressed in the tissues of the cisplatin‐resistant group and the cisplatin responsive group." (PMID 30993885, 2019). "Our observations suggest that PAK1 and Stat3 interact and colocalize in the nucleus in breast cancer cell lines." (PMID 31658701, 2019). "To investigate the direct recruitment of Stat3 to the promoter region of the IL-6 gene in breast cancer cells, we performed EMSA and ChIP assays." (PMID 31658701, 2019). "27-hydroxycholesterol induced activation of STAT-3, which promoted the angiogenesis of breast cancer cells via proinflammatory-related reactive oxygen species (ROS)/STAT-3/VEGF signaling." (PMID 31208017, 2019). "In breast cancer cells, honokiol inhibits the recruitment of Stat3 on mesenchymal transcription factor Zeb1 promoter, resulting in decreased Zeb1 expression and nuclear translocation." (PMID 31877856, 2019). "Toward this, the level of total STAT3 was assessed in three other breast cancer cell lines (Hs578T, MCF-7, and T74D) cell line." (PMID 31456939, 2019). "By inhibiting STAT3 phosphorylation, AG-490 is effective in reducing osteolysis and tumor growth of metastatic breast cancer, suggesting the potential of STAT3 as a therapeutic target in treating breast cancer bone metastases." (PMID 31040267, 2019). "Several studies have indicated that multiple pathways including PI3K/Akt, ERK, and STAT3 are engaged in breast cancer growth." (PMID 31243265, 2019). "STAT3 has a well-defined role in cancer progression, with over 40% of breast cancers presenting with constitutive STAT3 activation." (PMID 30847405, 2019).
breast cancer (continued). "There are many oncogenic molecules that are involved in the progression of breast cancer, and signal transducer and activator of transcription 3 (STAT3) protein can play a multifaceted role in breast tumorigenesis." (PMID 31058868, 2019). "In Her2+ breast cancer, STAT3 also promotes the epithelial-mesenchymal transition (EMT) and resistance to anti-microtubule agents." (PMID 31756933, 2019). "As indicated in a previous breast cancer cell line study, pSTAT1-pSTAT3 dimers bound on PD-L1 gene promoter inducing its expression and therefore STAT3 inhibition led to partial downregulation of PD-L1." (PMID 31581535, 2019). "STAT3 can be induced by the leukemia inhibitory factor in normal breast cells, whereas STAT3 is activated by IL-6 stimulation in breast cancer." (PMID 31058868, 2019). "In CD44+ CD24− basal-like breast cancer cells—indicative of a stem cell-like phenotype—the overactivation of STAT3 correlated with low metastasis-free survival and the induction of pro-invasive chemokines, IL-6, and TGF-β signaling." (PMID 31842362, 2019). "Using stable STAT3 reporter cells, we showed that niclosamide significantly reduced STAT3 activity in both cells and inhibit breast cancer cell motility by destabilizing focal adhesion complex formation." (PMID 31383893, 2019). "Specific inhibitors of FAK, Src and STAT3 showed that the effect exerted by leptin in cell migration in breast cancer cells is dependent on these proteins." (PMID 31671408, 2019). "We have previously reported human adipocytes induce EMT in MDA-MB-468 and MCF-7 breast cancer cells through paracrine IL-6 activation of STAT3, enhancing breast cancer cell migration and invasion, by induction of EMT19." (PMID 31383893, 2019). "Strikingly, here we demonstrated that inactivation of STAT3 signaling in all breast cancer cell lines tested involved a different mechanism." (PMID 31456939, 2019). "In our present study, the wild and overexpression of STAT3 MDA-MB-468 breast cancer cells were treated with dovitinib for 24 h and cell apoptosis and expression of STAT3/cyclin D1 axis were analyzed subsequently." (PMID 31485222, 2019). "Although we have previously shown that a high level of the adipocytokine visfatin in human breast cancer tissues correlated with tumor progression mediated by cAbl and STAT3, the effects of visfatin in the tumor microenvironment are unclear." (PMID 31861872, 2019). "We have recently reported that dual inhibitions of STAT1 and STAT3 constitutively inhibit PD-L1 expression in human breast cancer cells." (PMID 30915120, 2019). "This showed that honokiol can support crosstalk between LKB1, STAT3, and pluripotency factors in breast cancer and effective anticancer modulation of this axis with honokiol treatment in both in vitro and in vivo." (PMID 31877856, 2019). "The mitochondrial localization of STAT3 is required for its ability to support malignant transformation in murine embryonic fibroblasts and breast cancer cells, and mito-STAT3 regulates mitochondrial metabolism and mitochondrial gene expression." (PMID 31557897, 2019). "We have recently demonstrated that MH affects multiple functions of breast cancer cells through the inhibition of p-STAT3 functional activity and IL-6 secretion." (PMID 31491838, 2019). "In this line, recent data from human breast-cancer-studies suggest that leptin-activated STAT3, also promotes cancer cell stemness and chemoresistance through the expression of critical enzymes for acid β-oxidation pathways." (PMID 31380268, 2019). "We have shown dovitinib had significant antitumor effects in breast cancer cells with downregulation of p-STAT3 and its related molecules to result in cell apoptosis." (PMID 31485222, 2019).